HMGB1 (high mobility group box 1)
Diseases named in the same sentence as HMGB1 in open-access papers (continued):
Sharing a sentence is not in itself a finding about the gene and the disease.
diabetic cardiomyopathy (10 papers, 2014 to 2026). Diabetic cardiomyopathy is a disorder of the heart muscle in people with diabetes. "In diabetic cardiomyopathy, high glucose–induced mitochondrial ROS activates the circOGDH/HMGB1/RIPK3 axis in cardiomyocytes, leading to the activation of caspase-3, GSDMD, and p-MLKL, ultimately leading to heart failure." (PMID 41583472, 2025). "The most formal of an HMGB1/TLR4/IL-33 axis was recently shown in diabetic cardiomyopathy in mice where high glucose mediated cardiomyocyte HMGB1 release interacts with TLR4 on cardiac fibroblasts and results in decrease in IL-33." (PMID 28898270, 2017). "Inflammation, another pathologic process in diabetic cardiomyopathy, was confirmed by increased expression of HMGB-1 in the ventricular myocardium as well as increased inflammatory cell infiltration and TNF-α expression." (PMID 27847406, 2016). "In a mice model of diabetic cardiomyopathy, HMGB-1 inhibition ameliorated left ventricular remodeling." (PMID 27847406, 2016). "Similarly, by modulating the AGE–RAGE/HMGB-1 signaling pathway, which affects oxidative stress, inflammation, and fibrosis, artemisinin has been shown to contribute to the amelioration of diabetic cardiomyopathy." (PMID 39507806, 2024). "A cardiomyocyte HMGB1/fibroblast TLR4/IL-33 axis contributes to diabetic cardiomyopathy in mice." (PMID 28898270, 2017). "Inhibition of HMGB1 may be a target for therapeutic treatment of diabetic cardiomyopathy." (PMID 25210949, 2014).
diffuse large B-cell lymphoma (10 papers, 2015 to 2025). "It is worth noting that HMGB1 is overexpressed in malignant tissues, including lymphoid neoplasm diffuse large B‐cell lymphoma (DLBC), pancreatic adenocarcinoma (PAAD) and thymoma (THYM)." (PMID 35765707, 2022). "High mobility group box 1 (HMGB1) protein in the tumor microenvironment actively contributes to tumor progression but its role in diffuse large B-cell lymphoma (DLBCL) is unknown." (PMID 30988279, 2019). "Moreover, a recent study reported that both obinutuzumab and rituximab induced HMGB-1 release from diffuse large B-cell lymphoma (DLBCL) cells after a 4-h treatment." (PMID 28855903, 2017). "In the resting state of diffuse large B-cell lymphoma (DLBCL) cells, HMGB1 co-localized and interacts with STAT3 in the nucleus." (PMID 28969092, 2017). "Treatment of diffuse large B‐cell lymphoma (DLBCL) and mantle cell lymphoma (MCL) cell lines with 9‐cis‐retinoic acid (RA) and IFN‐α was found to exert therapeutic effects through the induction of CRT outgrowth, early HSP70/90 membrane exposure, CD47 downregulation, and enhanced HMGB1 secretion." (PMID 36815385, 2023).
Headache (10 papers, 2021 to 2025). Cephalgia, or pain sensed in various parts of the head, not confined to the area of distribution of any nerve. "Increased serum HMGB1 levels is associated with headache severity and paracetamol unresponsiveness in COVID-19 patients with headache." (PMID 38812640, 2024). "Innate immunity and damage-associated molecular pattern molecule HMGB1, and IL-6 were higher in COVID-19 headache patients and were correlated with headache severity and paracetamol unresponsiveness." (PMID 38369488, 2024). "NLRP3 was correlated with headache duration and hospital stay, while paracetamol response was negatively associated with HMGB1 levels and positively correlated with IL-10 levels." (PMID 34384355, 2021). "Serum NLRP3 levels were correlated with headache duration and hospital stay, while headache response to paracetamol was negatively correlated with HMGB1 and positively associated with IL-10 levels." (PMID 34384355, 2021). "Elevated HMGB1 level is significantly associated with the emergence of severe headache and correlated with paracetamol unresponsiveness in our patients with COVID-19 headache." (PMID 34384355, 2021). "In a MOH model in female rats using oral piroxicam, higher brain HMGB1 levels were shown to be positively correlated with headache behavior and elevated serum LBP levels." (PMID 38812640, 2024). "High-mobility group box 1 (HMGB1) is a master regulator in innate immunity and implicated in preclinical headache models and secondary headaches." (PMID 37940864, 2023). "Blocking Panx1 channels by TAT-Panx308 inhibited CSD-induced headache related behaviour and HMGB1 release." (PMID 37495957, 2023). "Elevated levels of HMGB1 and NLRP3 were implicated in the induction of the trigeminal system, with NLRP3 levels showed a moderate positive correlation with headache severity, length of hospitalization, and headache duration, while HMGB1 levels were positively correlated with headache severity." (PMID 40688353, 2025). "Serum LBP, occludin levels, and brain high mobility group box-1 protein (HMGB1) and interleukin-17 (IL-17) levels were significantly increased in male rats that manifested headache behavior such as reduced periorbital pain thresholds, increased grooming, freezing and head shakes." (PMID 38369488, 2024). "Increased serum HMGB1 could be related to inflammation induced both by intestinal hyperpermeability and headache pathophysiology in migraine patients." (PMID 38369488, 2024). "Next, we studied whether the acute effects of CSD on headache-related behaviour and cortical HMGB1 release could be prevented by blockade of neuronal Panx1 channels, as these channels open within minutes following a CSD and mediate an inflammatory cascade as part of trigeminovascular activation." (PMID 37495957, 2023). "More recently, HMGB1 was also shown to initiate an “inflammatory signaling cascade” in the brain parenchyma after a mild and brief disturbance, such as cortical spreading depolarization (CSD), leading to headache." (PMID 38082296, 2023). "While some studies have reported an association between the occurrence of headache and pro-inflammatory substances such as NLRP3, HMGB1, and interleukin 6, this has not been the case with all authors." (PMID 34979899, 2022). "Increased levels of the circulating inflammatory and/or nociceptive molecules like HMGB1, NLRP3, and IL-6 may play a role in the potential induction of the trigeminal system and manifestation of headache secondary to SARS-CoV-2 infection." (PMID 34384355, 2021). "They found that the serum level of high mobility group box-1 (HMGB1), Nod-like receptor pyrin domain-containing 3 (NLRP3), angiotensin-converting enzyme 2 (ACE2), and IL-6 was significantly higher among COVID-patients with headache compared patients without it." (PMID 35911910, 2022).
migraine (10 papers, 2019 to 2025). "A recent clinical study demonstrated a significant elevation in serum HMGB1 levels among migraine patients with drug overuse, potentially associated with trigeminal nerve sensitization." (PMID 40011963, 2025). "HDAC4 is highly expressed in the brain and is a major player in synaptic plasticity and modulates the expression and release of several neuroinflammation markers, including HMGB1 and NF-κB, which have been implicated in migraine pathophysiology." (PMID 38087366, 2023). "The extensive attention from researchers towards the involvement of HMGB1 in pain, including migraine, has positioned targeting HMGB1 as a valuable therapeutic strategy for pain management." (PMID 40011963, 2025). "It is noteworthy that scholars have engaged in a series of discussions regarding the role of HMGB1 in migraine." (PMID 40011963, 2025). "Entrance of LPS and HMGB1 into CNS in migraine patients would contribute to sustained central sensitization, neuroinflammation, migraine chronification and poor response to treatments." (PMID 38369488, 2024). "In the sepsis-associated multiple organ failure, riboflavin inhibits the release and expression of HMGB1, which is produced by neurons during the pathogenesis of experimental migraines." (PMID 34444772, 2021). "CSD is the electrophysiological equivalent of migraine aura which results in opening of Panx1 megachannels, neuronal HMGB1 release and induction of neuroinflammatory cascades in astrocytes that eventually result in neurogenic inflammation, trigeminal activation and headache." (PMID 39044141, 2024). "Further studies in larger populations will elucidate the role of HMGB1 in migraine and MOH." (PMID 38369488, 2024). "Also, the inflammatory profile, mainly NF-κB, plays an important role in the pathogenesis of a migraine, and NF-κB suppression by riboflavin might contribute to treating migraines by regulating inflammatory cytokines and HMGB1." (PMID 34444772, 2021). "We found elevated HMGB1 serum levels in CM patients with MOH and EM patients compared to healthy controls suggesting that HMGB1 could be a marker for migraine rather than chronicity." (PMID 38369488, 2024). "The high-mobility group box 1 (HMGB1) protein, which is a ubiquitously expressed non-histone DNA binding nuclear protein, has been related as an inflammatory mediator in CSD and migraine." (PMID 31607855, 2019).
neuropathic pain (10 papers, 2012 to 2025). Chronic pain caused by damage to nerve fibers. "In the present investigation, we examined the degree to which HMGB1 contributes to the peripheral sensitization of sensory neurons in a rodent tibial nerve injury (TNI) model of neuropathic pain." (PMID 22824385, 2012). "Neuropathic pain (NP) is a kind of chronic pain that has attracted much attention in clinical practice, characterized by high morbidity, complex mechanisms, and difficulties in clinical treatment, with which the activation of High mobility group box 1 (HMGB1) is closely related." (PMID 39359252, 2024). "We conclude that HMGB1 is a key protein during the nociception transmission at the spinal level, mainly during PCT-induced neuropathic pain." (PMID 38384464, 2024). "HMGB1 induces mechanical hypersensitivity and the blockade of TLRs, and RAGE has been shown to reduce hypersensitivity and pain behavior in neuropathic pain models." (PMID 34384355, 2021). "In vivo, EGCG can inhibit the expressions of TLR4, NF-κB, HMGB1, TNF-α, and IL-1β, and promote the expression of IL-10 in neuropathic pain rats." (PMID 24692852, 2014). "Taken together, these findings support the results of this study, reinforcing the proposition that HMGB1 participates in TLR4 spinal activation, triggering the production of inflammatory mediators involved with the nociception during PCT-induced neuropathic pain." (PMID 38384464, 2024).
pancreatic ductal adenocarcinoma (10 papers, 2016 to 2025). An infiltrating adenocarcinoma that arises from the epithelial cells of the pancreas. "HMGB1 holds significant potential as both a biomarker and therapeutic target in pancreatic ductal adenocarcinoma (PDAC)." (PMID 40495163, 2025). "Previous study has shown that upregulation of miR-410-3p enhanced the chemoresistanc of pancreatic ductal adenocarcinoma by targeting HMGB1 and suppressing HMGB1-mediated autophagy." (PMID 32709223, 2020). "Pancreatic ductal adenocarcinoma patients with elevated serum HMGB1 levels have a poor prognosis." (PMID 36831371, 2023).
schizophrenia (10 papers, 2021 to 2025). A major psychotic disorder characterized by abnormalities in the perception or expression of reality. "HMGB1 was also found among Danger-/damage-associated molecular patterns which were reported for elevated serum levels in schizophrenia." (PMID 37280213, 2023). "Moreover, there are some associations between serum HMGB1 levels and clinical symptoms in patients with schizophrenia." (PMID 35743957, 2022). "The aim of this study was first to check the association of HMGB-1 levels with two different phases of schizophrenia, i.e, acute exacerbation phase andremission phase and compare them with healthy controls (control group); and second to relate HMGB-1 to symptom scores,in relation to disease phase." (PMID 34177374, 2021). "There is no statistically significant variation in biomarker levels between acute and remission phases of schizophrenia, and HMGB1 levels in remission-phase patients correlate with the severity of symptoms assessed by psychiatric scales." (PMID 40557138, 2025). "Quantitative subcellular proteomics of the orbitofrontal cortex of patients with schizophrenia also showed overexpression of HMGB1 (among other things)." (PMID 37298365, 2023). "One experiment that examined the interactions of schizophrenia with 504 different proteins showed that HMGB1 is a protein of importance in the pathogenesis of the disease." (PMID 37298365, 2023). "Studies have shown that Fibromyalgia and Chronic Fatigue Syndrome Score (FF) are positively correlated with HMGB1 in patients with schizophrenia." (PMID 35743957, 2022). "Related studies on serum HMGB1 levels in schizophrenia patients have obtained a relatively consistent result." (PMID 35743957, 2022). "In this study, HMGB-1, as an inflammatory marker, was evaluated in patients suffering from acute exacerbation and in patients with chronic remission of schizophrenia." (PMID 34177374, 2021). "The aim of this study was to evaluate HMGB-1 levels among patients with schizophrenia both in acute exacerbation and remission phases." (PMID 34177374, 2021). "Schizophrenia patients display higher serum HMGB1 levels than controls." (PMID 40557138, 2025). "Interestingly, the serum level of HMGB1 in patients with schizophrenia is significantly higher than in healthy donors." (PMID 36834811, 2023). "The possibility that stress-induced HMGB1 release could chronically activate the immune system in schizophrenia patients due to dysfunction of immune tolerance mechanisms is another novel concept put forward in this paper." (PMID 35844244, 2022). "It suggested that an inflammatory response characterized by elevated HMGB1 levels could persist in the acute or chronic course of schizophrenia." (PMID 35743957, 2022). "Recent studies have shown that HMGB1 plays an important role in schizophrenia." (PMID 35743957, 2022). "More studies are needed to investigate the functions of HMGB1 in patients with schizophrenia." (PMID 35743957, 2022). "Hence, in order to precisely delineated the temporal relationship of HMGB-1 with the symptoms of schizophrenia, blood samples should be obtained from drug-naive patients with schizophrenia in the first-episode on longitudinal studies." (PMID 34177374, 2021). "Additionally, ithas been suggested that HMGB1’s neurotoxic effects may contribute to theneurocognitive impairments and various symptom clusters observed in schizophrenia." (PMID 41209506, 2025). "Therefore, it seems that HMGB-1 might potentially be a marker of chronic disease status of schizophrenia, though it remains to be established in larger longitudinal cohorts in relation to therapy." (PMID 34177374, 2021). "In the remission phase of schizophrenia patients (Group 2), age, duration of illness, number of previous hospitalizations and HMGB-1 levels were enrolled into regression analysis and it was found that HMGB-1 levels were independently associated with BPRS in linear regression analysis." (PMID 34177374, 2021).
schizophrenia (continued). "The serum level of HMGB1 is significantly higher in male patients with schizophrenia than in healthy subjects, which does not depend on the episode and treatment." (PMID 35743957, 2022). "On the other hand, HMGB-1 levels seem to be positively correlated with symptom severity scores in patients with remission phase of schizophrenia, whereas, the biomarker levels do not relate to symptom scores in acute exacerbation phase." (PMID 34177374, 2021). "Currently, we do not know whether changes in serum HMGB1 before and after antipsychotic treatment can be used to assess treatment response, and the exact dynamics of schizophrenia remain unclear." (PMID 35743957, 2022). "Serum HMGB-1 levels were shown to be increased in patients with schizophrenia with or without acute exacerbation and higher in patients with schizohprenia compared to healthy controls, and hence, do not differ significantly in remission phase versus acute exacerbation." (PMID 34177374, 2021).
systemic sclerosis (10 papers, 2011 to 2021). A chronic disorder, possibly autoimmune, marked by excessive production of collagen which results in hardening and thickening of body tissues. "Here, we discuss recent evidence that implicates the prototypic damage-associated molecular pattern/alarmin, the high mobility group box 1 (HMGB1) protein in systemic vasculitis and in the vascular inflammation associated with systemic sclerosis." (PMID 27242789, 2016). "The role of RAGE in skin remodeling and systemic sclerosis is already a defined process, worth mentioning also in this review: among other alarmins such as IL-33 and IL-1α, HMGB1 seems to play a major role as a ligand for the RAGE receptor." (PMID 33435332, 2021). "Microparticles from activated platelets express high-mobility group box 1 protein, a damage-associated molecular pattern, and promote vasculopathy and NET formation in patients with systemic sclerosis and in a murine model." (PMID 31338092, 2019). "Although there have been few studies on the relationship between HMGB-1 and fibrosis or scarring, the serum level of HMGB-1 has been positively correlated with skin thickness in systemic sclerosis." (PMID 28771195, 2017). "Similarly, the release of activated platelet-derived microparticles enriched with high-mobility group box 1 (HMGB1) protein has been described in systemic sclerosis." (PMID 33304353, 2020). "Furthermore, HMGB1 contained in PLT-derived MV is released during PLT activation in patients with systemic sclerosis." (PMID 29375570, 2017). "It is also in agreement with studies showing that increased HMGB1 and RAGE expression was detected in fibroblasts in fibrotic skin lesions from patients with systemic sclerosis." (PMID 21365018, 2011).
amyotrophic lateral sclerosis (9 papers, 2017 to 2024). Amyotrophic lateral sclerosis (ALS) is a neurodegenerative disease characterized by progressive muscular paralysis reflecting degeneration of motor neurons in the primary motor cortex, corticospinal tracts, brainstem and spinal cord. "Furthermore, HMGB1 is implicated in the pathogenesis of other neurodegenerative diseases such as amyotrophic lateral sclerosis (ALS) and Huntington’s disease." (PMID 39507236, 2024). "Despite this, HMGB1 has historically been viewed through the lens of its nuclear effects, including maintenance of genome stability, replication, and repair, making HMGB1 relevant in diseases of overt nuclear changes, such as amyotrophic lateral sclerosis and mutations giving rise to cancer." (PMID 28531105, 2017). "Multiple investigations suggest a role for HMGB1 in amyotrophic lateral sclerosis (ALS)." (PMID 30210286, 2018).